ZEB1 (zinc finger E-box binding homeobox 1)
Diseases named in the same sentence as ZEB1 in open-access papers (continued):
Sharing a sentence is not in itself a finding about the gene and the disease.
tumor (continued). "We describe the case of a plasmacytoid urothelial carcinoma of the renal pelvis in which the expression of zinc finger E–box–binding homeobox 1 (ZEB1), a key nuclear transcription factor in an epithelial–mesenchymal transition, is involved in tumor transformation." (PMID 33032610, 2020). "Therefore, understanding the function of transcriptional factors such as Snail1, Twist1, and Zeb1 is necessary to achieve a more comprehensive understanding of tumor EMT." (PMID 32028978, 2020). "For E-cadherin, claudin-1, vimentin, and nuclear Snail/Slug expression, these differences occurred in both the tumor center and the tumor margin, whereas significantly higher levels in surgically resected samples were observed only at the tumor margin for ZEB1." (PMID 32093260, 2020). "Indeed, we found that inhibition of ZEB1 counteracted the effects of AGR2 knockout on the invasiveness of tumor cells, as shown by the invasion assay." (PMID 32570918, 2020). "In addition, depletion of CDK4/6 activity by treatment with Lee011 and shRNA knockdown was used to verify that CDK4/6 inhibition reversed the EMT phenotype and prevented tumor cell metastasis through the regulation of ZEB1 in vitro." (PMID 32296027, 2020). "Furthermore, we observed that CD31-positive endothelial cells in PyMT-Fib-cKO tumours expressed comparable levels of ZEB1 relative to PyMT-Fib-WT tumours, suggesting that FSP1-Cre does not target endothelial cells in our system." (PMID 31324807, 2019). "By deriving a set of ZEB1 activated and correlated genes, we demonstrated that ZEB1 transcriptional activity is also correlated with decreased tumor immune activity and provided a set of potential functional regulators of the tumor immune response for further investigation." (PMID 31780722, 2019). "Furthermore, signals downstream of WNT/β-catenin, including the TCF4/ZEB1 signal, the tumor stemness pathway, and EMT, were shown to be downregulated in FOXO1-overexpressing NPC cells." (PMID 31754475, 2019). "Additionally, tumor suppressor miR-142-5p was predicted to target SREBP1/ZEB1 and a lower miR-142-5p was correlated with poor prognosis." (PMID 31861383, 2019). "Besides, median pre-treatment rate of positive tumor cells for c-myc, Cyclin D1, and Zeb-1 were 30% (range 10–60%), 50% (15–60%), and 12% (5–25%), respectively." (PMID 31390375, 2019). "Restoring ZEB1 rescues miR-455-induced suppression of tumor progression." (PMID 30813457, 2019). "The zinc-finger transcription factor ZEB1 has been widely recognised as an important driver of tumour invasion, distant metastasis, drug resistance and radioresistance by inducing the epithelial-to-mesenchymal transition programme (EMT) in tumour epithelial cells." (PMID 31324807, 2019). "Indeed, we have previously identified that tumor cells maintaining the ZEB1 promoter in a bivalent chromatin configuration are highly conducive to activating the EMT program, or part thereof." (PMID 31623163, 2019). "The novel putative intestinal and pancreatic stem cell marker DCAMKL-1, a microtubule-associated kinase, plays a key role in tumorigenesis by downregulating tumor suppressor microRNAs thus inducing tumor promoters specific targets such as ZEB1, ZEB2, and Notch-1." (PMID 31861725, 2019). "CD8+ T cell suppression within the tumor microenvironment is dependent on PD-L1 regulation on tumor cells via a pathway involving the microRNA miR-200 and the transcription factor ZEB1; these molecules are the links between EMT, CD8+ T cell exhaustion, and tumor suppression." (PMID 31137625, 2019). "Consistently, RP11 increased Zeb1 expression in HCT-15 tumour xenografts." (PMID 30979372, 2019). "Predominant nuclear expression of ZEB1 is observed in 28% of tumours." (PMID 31543517, 2019).
tumor (continued). "However, accumulating evidence indicates that ZEB1 protein is predominantly present in tumour stromal cells in various human cancer samples, including breast cancer." (PMID 31324807, 2019). "Stroma-corrected ZEB1 expression was significantly inversely correlated with five out of seven “steps” of the immune cycle: Antigen release, immune cell priming and activation, immune cell recruitment to the tumor, tumor infiltration, and cell killing." (PMID 31780722, 2019). "Additionally, ZEB1 expression in pathologic specimens correlated with advanced tumor grade and worse outcomes." (PMID 31681587, 2019). "Therefore, we performed RT-qPCR to evaluate ZEB1 mRNA expression levels and found that they were higher in OS specimens than adjacent non-tumor tissues (P < 0.05)." (PMID 30846940, 2019). "Of note, ZEB1 can suppress E-Cadherin expression and promote tumor cell dedifferentiation." (PMID 31405071, 2019). "Future studies will be required to determine whether ZEB1 influences the activity of Rab7 through regulation of TBC1D2a during normal development and tumor metastasis." (PMID 31719531, 2019). "Furthermore, in order to confirm the positive correlation between RAE1 and ZEB1 in an in vivo system, IHC was performed with anti-ZEB1 antibody in tumor tissues retrieved from the xenograft experiment." (PMID 30814639, 2019). "Furthermore, while in overexpressing ALDH3A1 tumor cells the EMT markers Zeb1 and cMYC, known to be associated with PD-L1 expression, were upregulated, in ALDH3A1-ablated tumor cells they were downregulated." (PMID 31817719, 2019). "The ZEB1 expression might also take advantage of tumor progression by various means related to metastasis initiation, stemness, cellular survival, and metabolic plasticity." (PMID 31331982, 2019). "Interestingly, the enhancement of PTEN and CD36 and the reduction in Snai1 and Zeb1 mRNA expression in the tumor tissue by ApoSQ injection were reversed by GW9662 treatment." (PMID 30842627, 2019). "Accordingly, previous literatures have revealed that ZEB1 could activate the transcription of certain lncRNAs in tumor cells, but the effect of ZEB1 on SNHG14 was firstly revealed in this study." (PMID 31570691, 2019). "Thus, tumor budding cells have been shown to have reduced expression of miR‐200b and miR‐200c, while on the other hand they exhibit increased expression of ZEB1 and ZEB2." (PMID 31295960, 2019). "ZEB1 is a zinc finger/homeodomain protein that is associated with EMT and tumor progression." (PMID 31681587, 2019). "Importantly, a single-ApoSQ injection leads to the enhanced induction of PPARγ and PTEN mRNA and protein expression and to a reciprocal reduction in phosphorylated Akt, as well as in the mRNA levels of Snai1 and Zeb1, within primary tumor tissue." (PMID 30842627, 2019). "Taken together, we hypothesized that PTGDS inhibits EMT and suppresses tumor proliferation and invasion by regulating the expression of ZEB1 and Slug in DLBCL." (PMID 30393234, 2019). "In the MDA-MB-231 xenograft tumor tissues, ZEB1 was expressed mainly in the nucleus." (PMID 30814639, 2019). "The presence of EMT-associated key genes such as SNAIl1, Twist and ZEB1 in stromal cells in colon tumors could signify that a subset of tumor cells undergo EMT, particularly at the tumor invasive front." (PMID 29495500, 2018). "We propose that SDC-1 repression by ZEB1 occurs mainly in epithelial cells without oncogene or tumor suppressor mutations." (PMID 30065348, 2018). "Additional studies have reiterated the behavior of ZEB1 as a tumor suppressor." (PMID 32309604, 2018). "Moreover, ZEB1 depletion resulted in a more differentiated state of tumor cells and an increased expression of Gata6, a marker of differentiation in PDAC." (PMID 29373514, 2018).
tumor (continued). "Previous studies have collectively offered evidence for the detection of EMT in circulating tumor cells and conducted gain‐of‐function/loss‐of‐function assays targeting EMT‐inducing transcription factors such as Twist, Snail, Slug, and Zeb1." (PMID 30120146, 2018). "The present study is the first to report the prognostic relevance of ZEB1 expression in IPMN, and supports the hypothesis that treatment strategies targeting ZEB1 may also target tumor cells, as well as stromal cells." (PMID 29416615, 2018). "Moreover, ZEB1 expression was positively correlated with expression of B-cell lymphoma-extra large (Bcl-xL) and cyclin D1, which are key components of tumor chemoresistant mechanisms." (PMID 29352223, 2018). "The rfhSP-D treatment of these cell lines for up to 24 h prevented their morphological alterations associated with EMT, reduced tumor cell invasion in the matrigel, downregulated TGF-β production, and downregulated key mesenchymal gene expression, such as Vimentin, Zeb1, and Snail." (PMID 30158928, 2018). "Thus, an EMT regulatory program for the exhaustion of CD8p tumor-infiltrating lymphocytes and immunosuppression of PD-L1 via the miR-200/ZEB1 axis is critical to tumor metastasis." (PMID 29723992, 2018). "ZEB1 deletion was associated with poor overall survival (OS) with and without adjustment for age and tumor grade (adjusted HR: 4.25; 95% CI: 2.35 to 7.66; P < 0.001)." (PMID 30705664, 2018). "After correcting for possible over-fitting, there was a trend toward improved predictive accuracy by adding ZEB1 copy number to the base model including age and tumor grade (change in optimism-corrected c-statistics: 0.02; 95% CI: −0.01 to 0.05) though it was not statistically significant." (PMID 30705664, 2018). "Cancer cells that encounter a combination of different signaling molecules like PDGF, HGF, TGF-β1, or EGF among many others secreted by the complex tumor microenvironment orchestrate the gene expression of cancer cells for instance by upregulation of transcription factors like snail, twist, or zeb1." (PMID 30347648, 2018). "In this study, ZEB1 expression in the epithelial cell was observed only in 3 cases (3.4%), which is comparable with that reported in a previous study (2%) and consistent with the notion that cancer stem cells occur rarely in the tumor cell population." (PMID 29416615, 2018). "A reciprocal feedback loop between the miR‐200 family and ZEB1/2 transcription factors plays a central role in epithelial cell plasticity, and by virtue of its potency functions widely in controlling cell invasiveness, stemness and tumour metastasis." (PMID 29871889, 2018). "We have shown that Zeb1 is important for tumor progression in K-Ras-initiated lung cancer." (PMID 29930325, 2018). "In addition, Zeb1 knock-out in orthotopic mouse xenograft models significantly affected the tumor growth and EMT by switching the expression of Vimentin and E-cadherin." (PMID 30158928, 2018). "ZEB1 also facilitated tumour cell migration, invasion and clonogenicity." (PMID 29754422, 2018). "Collectively, our findings suggested that SNHG16 could act as an oncogenic lncRNA that promotes tumor progression through acting as an endogenous ‘sponge’ by competing with miR-140-5p, thereby regulating target ZEB1." (PMID 29416674, 2018). "Interestingly, an analogous expression threshold has been reported for ZEB1 tumor-promoting functions." (PMID 30304480, 2018). "A good correlation was found between the circ-ZEB1.33 value of serum and tumor tissue." (PMID 30123094, 2018). "In addition, a number of studies have reported the regulation of ZEB1 expression in tumor cells through different signaling cascades including the AKT and ERKs pathways." (PMID 30158599, 2018).
tumor (continued). "Importantly, we also found that AMG232 is highly efficacious in three-dimensional (3D) tumor spheroids growth and effectively inhibits the stemness-related factors, Nestin and ZEB1." (PMID 30022047, 2018). "Finally, we sought to determine the relative importance of Zeb1 vs. other miR-200 targets in tumor progression." (PMID 30405106, 2018). "The tumor suppressive effect of lncRNA knockdown could be restored by re-expression of ZEB1 in CRC cells." (PMID 28837144, 2017). "What’s more, the suppression of tumor phenotype by knockdown of lncRNA XIST could be restored by ectopic expression of ZEB1 or inhibition of miR-200b-3p (*P<0.05)." (PMID 28837144, 2017). "Moreover, a correlation between LKB1 downregulation and ZEB1 upregulation with concomitant induction of EMT in tumor cells has been described." (PMID 28700115, 2017). "When ZFAS1 is upregulated in HCC, is hypothesized to act as a sponge to decrease the concentration of miR-150, thereby upregulating ZEB1, which induces tumor cell invasion and metastasis in in vitro and animal models." (PMID 28333948, 2017). "In this manuscript, the authors reveal that Notch1 activation and EMT promote tumor initiation and cancer cell heterogeneity in squamous cell carcinoma, while the repression of Notch3 by ZEB1 limits Notch1-induced differentiation, permitting Notch1-mediated EMT." (PMID 29170450, 2017). "Moreover, ZEB1 can also promote tumor invasiveness via the regulation of players involved in stroma remodeling: the urokinase plasminogen activator (uPA), and its inhibitor, plasminogen activator inhibitor-1 (PAI-1)." (PMID 29258163, 2017). "In MCL, also an important role for ZEB1 in tumor aggressiveness has been identified." (PMID 28556516, 2017). "ZEB1 tumour expression was significantly higher in patients treated with docetaxel." (PMID 28133913, 2017). "Considering our findings, we propose that ZEB1 is a key regulator of breast CSCs and may be critically involved in tumor initiation." (PMID 28903350, 2017). "To check whether ZEB1 binds and represses CDKN1A and CDKN2A genes in human tumor cells, we conducted ChIP assays and found that ZEB1 was indeed bound to CDKN1A promoter, implying a direct regulatory role for ZEB1 to promote cell proliferation in UM cells." (PMID 28246385, 2017). "Unexpectedly, ZEB1 staining intensity increased towards the tumor center." (PMID 28945795, 2017). "Irrespective of EGFR or IDH status or the observed heterogeneity of ZEB1 in the parental tumor, ZEB1 was homogeneously expressed in virtually all cells of all four cell lines, which could be quantified by image cytometry." (PMID 28945795, 2017). "In summary, ZEB1 is expressed by nearly all tumor cells but a varying expression levels." (PMID 28945795, 2017). "Since ZEB1 may affect different steps in the tumorigenic process, more detailed studies are needed to elucidate its possible contribution to tumor initiation and expansion." (PMID 28903350, 2017). "Furthermore, high expression of ZEB1 is shown to be significantly correlated to tumor scleral invasion and metastasis." (PMID 28246385, 2017). "Thus, given this mutual exclusivity of ZEB1 expression in tumor vs. immune cells, the amount of immune infiltration will invariably be reflected in the overall ZEB1 labelling index of human GBMs." (PMID 28945795, 2017). "It is thus likely that nearly all tumor cells stain positive for ZEB1." (PMID 28945795, 2017). "Knockdown of ZEB1 reduced the invasive properties of this aggressive tumor." (PMID 28556516, 2017). "We also found that ZEB1 enhanced tumor growth when HCC1954‐Luc cells were grafted into nude mice." (PMID 28618162, 2017). "In addition to this canonical EMT signaling, ZEB1 has lately been shown to be involved in DNA damage response and modulation of tumor induced immunosuppression." (PMID 28945795, 2017).
tumor (continued). "Furthermore, with analysis by a real-time qPCR, key transcriptional factors of the EMT such as Snail1, Snail2, Twist1, Twist2, Zeb1, and Zeb2, were found to be markedly expressed in Tg-6m tumor cells when normalized to Tg-3m tumor cells." (PMID 28419107, 2017). "In contrast, we observed variable staining intensities in ZEB1+ tumor cells." (PMID 28945795, 2017). "One could make the argument that ZEB1 may be highly expressed in cells that are involved in tumor invasion, accounting for a small fraction of the tumor cells which have highly invasive properties." (PMID 28246407, 2017). "HAS2 is involved in tumor progression and acts in concert with ZEB1-driven EMT." (PMID 28086235, 2017). "Moreover, Zeb1 expression persists in MB tumor cells, the transformed GNP counterpart in which SHH signaling is persistently activated." (PMID 27178982, 2016). "Tumor size, cell type (clear/granular), Fuhrman’s grade, Staging, as well as immunostaining with Snail, ZEB1, Twist, Vimentin, E-cadherin, β-catenin, PTEN, p-Akt, p110α, and SETD2, were analyzed for intratumor heterogeneity using a classification and regression tree algorithm." (PMID 26951092, 2016). "High levels of ZEB1 protein could be detected in both MITFhigh and MITFlow clones after vemurafenib treatment, even within the same tumor (patient 1)." (PMID 27596438, 2016). "These authors showed that these miRNAs cooperatively regulate the expression of the E-cadherin transcriptional repressors zinc finger E-box binding homeobox 1 (ZEB1; also known as deltaEF1) and SIP1 (also known as ZEB2), factors previously implicated in EMT and tumor metastasis." (PMID 26563372, 2016). "Zeb1 and Twist1 transcript expression in the recovered tumor cells was determined by cDNA qPCR." (PMID 27270319, 2016). "ZEB1 was proved to be related to tumor genesis and metastasis." (PMID 27036021, 2016). "We wanted to rule out that activation of a common ZEB1/YAP target gene pattern important for tumour progression is a general EMT-associated effect on the Hippo pathway and its effectors, which is indirectly and unspecifically exerted by different EMT-inducers." (PMID 26876920, 2016). "ZEB1 expression in tumour cells of human cancers is heterogenous." (PMID 26876920, 2016). "Data from multiple large tumor sets from The Cancer Genome Atlas (TCGA) reveals that CRKL expression is negatively correlated with miR-200 family expression, positively associated with ZEB1, EMT status, and Src signaling." (PMID 26728244, 2016). "Members of the EMT regulating transcription factor families such as SNAI1/2, TWIST1/2 and ZEB1/2, are well-known as key inducers of invasion and metastasis in epithelial cancers through the conversion of tumour cells from an epithelial to a mesenchymal-like state." (PMID 27470974, 2016). "Compared with those from other groups, the expression of TGF-β1, Vimentin, ZEB-1, N-cadherin, Gli1/2, and P-Smad2/3 was significantly decreased in the tumor areas from the mice vaccinated with B16F10/GPI-IL-21 combined with the B16F10/shTGF-β1 challenge and the administration of miR200c agomir." (PMID 25895132, 2015). "We hypothesised that the induction of miR-200c by natural products may have a similar effect on ZEB1 and E-cadherin expression, leading to tumour suppression." (PMID 26423775, 2015). "In addition, the results in vivo further demonstrated that lower tumor proliferation and dramatic less liver metastasis were appeared both in miR-652 overexpression and ZEB1 knockdown xenotransplantation models." (PMID 26498682, 2015). "Additionally, ZEB1 knockdown in tumour cells abolished VM formation, led to epithelial phenotype restoration, and evidently repressed tumour migration and invasion." (PMID 25598425, 2015). "Tumor suppressors miR-15a and miR-16 regulate tamoxifen sensitivity by targeting Bcl-2, miR-451 targets 14-3-3ζ, let7s target ER-α36, miR-375 targets metadherin and miR-200b/c target ZEB1." (PMID 26206152, 2015).